HOXB8 (homeobox B8)
Diseases named in the same sentence as HOXB8 in open-access papers (continued):
Sharing a sentence is not in itself a finding about the gene and the disease.
tumor (20 papers, 2009 to 2025). "siHOXB8 PANC-1 cells exhibited impaired cell proliferation, but also suppressed induction of tumor-associated macrophages illustrating that HOXB8 contributes to both the pancreatic progenitor and immunogenic features observed in the immunogenic PDAC subtype." (PMID 40619489, 2025). "To identify the global transcriptional changes underlying HOXB8-mediated suppression of MEK1ca-induced neoplasia, we performed RNA-Seq on GFP-sorted positive neural tube cells." (PMID 34445617, 2021). "While SAMD9 has been characterized as a tumor suppressor in lung, breast, and colon cancer, its role in glioma is paradoxical, as it has been reported to drive tumor progression by regulating HOXB8." (PMID 41331572, 2025). "First, we examined if reduced HOXB6 and HOXB8 expression affected clonogenic capacity of tumor cells by performing colony formation assays." (PMID 40619489, 2025). "Co-culture of HOXB6 and HOXB8 deficient PDAC cells with macrophages confirmed that HOXB6 and HOXB8 promoted tumorigenic properties of tumor-associated macrophages and protected PDAC cells from macrophage detection." (PMID 40619489, 2025). "This illustrates that HOXB8 has a critical role in tumor-immune cell interaction by modulating macrophage differentiation towards a more tumor-supportive cell state." (PMID 40619489, 2025). "In conclusion, the RNASeq results, validated by in situ hybridization, and the gene ontology analysis, are consistent with the phenotypic tumor suppressor effect of the HOXB8 gain of function in the MEK1ca-neoplasia-induced context observed morphologically." (PMID 34445617, 2021). "The HOXB8 tumor suppressor function relies on a large reversion of the oncogenic transcriptome induced by ERK." (PMID 34445617, 2021). "We next decided to investigate the molecular mechanisms by which HOXB8 inhibits ERK1/2 overactivation-induced neoplasia." (PMID 34445617, 2021). "At the same time, HOXB8 also showed upregulation in EOC tumor samples in two GSE datasets with one dataset reached a marginal significant p-value." (PMID 33815481, 2021). "This morphological analysis suggested that in this context, the HOXB8 gain of function works as a tumor suppressor." (PMID 34445617, 2021). "Transcriptomic analysis showed that the HOXB8 tumor suppressor function relies on a large reversion of the oncogenic transcriptome induced by ERK overactivation." (PMID 34445617, 2021). "Altogether, these results show that HOXB8 functions as a tumor suppressor in this neoplasia context by increasing cell death and preventing MEK1ca-induced target gene activation, acting downstream of ERK phosphorylation and nuclear translocation." (PMID 34445617, 2021). "It would thus be interesting to investigate if other HOX proteins behave as HOXB8 in the specific context of MEK1ca neoplasia induction in the embryonic neural tube." (PMID 34445617, 2021). "Tumor stage (p < 0.0001), lung metastasis (p < 0.0001), tumor relapse (p = 0.0067), and chemoresistance (p < 0.001) are positively correlated with HOXB8 staining." (PMID 34432948, 2021). "Among these upregulated DEGs, PNCK, HOXA9, and HOXB8 were all reported to be related to tumor progression in several cancers." (PMID 33318296, 2020). "Another candidate HOXB8, similarly to HOXA1, was a member of HOX family that was found to be significantly linked with tumor metastasis and shorter overall survival in many human cancers." (PMID 31787845, 2019). "Compared with the normal tissues, most of the HOX genes showed increased expression in tumor tissues, only HOXB1 and HOXD1 decreased expression in PGs samples, and the difference in expression of these HFGs in normal and tumor tissues was statistically significant except HOXB8 and HOXC12." (PMID 37547473, 2023). "In addition, the activation of the miR-133b/HOXB8 axis also promotes tumor stemness, proliferation and invasion." (PMID 35769986, 2022). "It acts as a tumor suppressor in non-small cell lung cancer (NSCLC) by targeting the HOXB8 gene." (PMID 36276982, 2022).
tumor (continued). "We found that HOXB8 largely counteracts ERK oncogenic activity in this neoplasia model." (PMID 34445617, 2021). "The low level of HOXB8 reduced the OS of ccRCC; however, we found that HOXB8 may also control tumor invasion by inhibiting CCND1 and MYC in the Wnt signaling pathway." (PMID 34306077, 2021). "The hits are coherent with the tumor suppressor role of HOXB8 in this context." (PMID 34445617, 2021). "In addition to confirm the RNA-Seq data, the study of LIN28A regulation by MEK1ca and HOXB8, together with LIN28A oncogenic activity, suggested that HOXB8 reversion of MEK1ca neoplasia at least partly relies on transcriptional downregulation of LIN28A." (PMID 34445617, 2021). "Since HOXB8 overexpression in the neural tube leads to an increase of apoptosis, HOXB8 tumor suppressor effect may be due to cell death induction in MEK1ca expressing cells." (PMID 34445617, 2021). "We found that HOXB8 acts as a tumor suppressor, counteracting ERK-induced neoplasia." (PMID 34445617, 2021). "LZTS1 is transcriptionally activated by HOXB8 and might, as other genes from the same cluster, provide additional mechanisms by which HOXB8 reverses MEK1ca-induced neoplasia." (PMID 34445617, 2021). "Furthermore, tumor-promoting function generated through silencing miR-133b was saved by knocking down HOXB8 confirmed by the rescue assays of EdU, spheroid formation and transwell." (PMID 31978895, 2020). "Finally, the effect of ZEB1-AS1/miR-133b/HOXB8 in nude mice was investigated via subcutaneous tumor formation experiments." (PMID 31978895, 2020). "Silencing of HOXB8 inhibited tumor growth, all these tumors were further verified by H&E staining." (PMID 30622439, 2019). "Next, we aimed to explore the function of HOXB8 in tumor growth in vivo." (PMID 30622439, 2019). "30.4% (704/2316) of the genes (clusters 6–8) behaved oppositely to the genes of clusters 1–5: their expression was downregulated by MEK1ca (MEK1ca versus pCIG) and reversed by HOXB8 (upregulated in “MEK1ca + HOXB8 versus MEK1ca”), and thus might contain new putative tumor suppressors." (PMID 34445617, 2021). "Subsequently, the rescue assays of proliferation, tumor stemness, and invasion also testified that cancer-promoting effect caused by ZEB1-AS1 overexpression was saved by knocking down HOXB8, indicating that ZEB1-AS1 promoted malignant progression of CCA partly by promoting HOXB8." (PMID 31978895, 2020). "Hence, we suggest that our findings might be relevant for a variety of human tumour cell types and, based on our HoxB8 progenitor results, that the mechanism reported may also be conserved from mice to men." (PMID 25922916, 2015). "Meanwhile, significant differences in METTL7B, HOXB8, and TREM1 were found between the controls and tumor samples in both mRNA levels." (PMID 38376699, 2024). "Using an in vivo neoplasia model in the chicken embryo consisting in the overactivation of the ERK1/2 kinases in the trunk neural tube, we analyzed the consequences of the HOXB8 gain of function at the morphological and transcriptional levels." (PMID 34445617, 2021). "To test the effect of HOXB8 on ERK oncogenic activity in an in vivo context, we took advantage of a model of ERK-induced neoplasia we developed in the chicken embryo neural tube." (PMID 34445617, 2021). "Notably, low expression levels of HOXB8 and TREM1 significantly correlated with a low tumor recurrence rate." (PMID 38376699, 2024). "The data presented also suggest several non-exclusive mechanisms though which HOXB8 acts as tumor suppressor in the neural tube downstream of oncogenic ERK activation." (PMID 34445617, 2021). "For example, tumor cell behavior (proliferation, apoptosis, senescence) in response to reduced HOXB6 and HOXB8 expression could be observed and co-culture experiments with M0 macrophages allowed us to study if HOXB6 and HOXB8 are important for immune-cancer cell interactions." (PMID 40619489, 2025).
cancer (17 papers, 2012 to 2025). A tumor composed of atypical neoplastic, often pleomorphic cells that invade other tissues. "To determine if HOXB6 and/or HOXB8 regulate the immune response specifically in PDAC, we performed a TIMER association analysis of HOXB6 and HOXB8 expression with all TCGA cancer samples currently included in this analysis module." (PMID 40619489, 2025). "From the 40 cancer types studied, HOXB6 and HOXB8 expression correlated with cancer-associated fibroblast and myeloid-derived suppressor cell infiltration in 7 different types of cancer." (PMID 40619489, 2025). "Certain proteins in cancer cells (e.g., Yes1 associated transcriptional regulator [YAP], homeobox B8 [HOXB8], and FOS like 1 [FOSL1]) promote condensate formation, thus directly enhancing oncogene expression and cell proliferation." (PMID 40032852, 2025). "Studies have shown that the HOXB gene cluster contributes to cancer development; increased expression of HOXB3, HOXB6, HOXB7, HOXB8, and HOXB9 in LUAD patients is linked with poor overall survival (OS)." (PMID 36506331, 2022). "Indeed, miR-196 may play a critical role in cancer pathogenesis by targeting several regulation molecules including HOXB8, HMGA2, and annexin A1." (PMID 35563269, 2022). "RNA-seq and ChIP-seq analyses showed that HOXB6 and HOXB8 directly regulate expression of genes critical for cell proliferation (HOXB6) and immune-cancer cell interaction (HOXB6 and HOXB8)." (PMID 40619489, 2025). "The results showed that some HOX genes in pan-cancer had significant strong correlation (R≥0.8): HOXA9 with HOXA10, HOXB5 with HOXB6 and HOXB8, HOXB8 with HOXB6 and HOXB9, HOXB3 with HOXB4 and HOXB5 and HOXB6, HOXC8 with HOXC9, HOXC9 with HOXC10, HOXD10 with HOXD11." (PMID 39980564, 2025).
infection (11 papers, 2013 to 2025). The state of being infected such as from the introduction of a foreign agent such as serum, vaccine, antigenic substance or organism. "For MIP-1α and RANTES production, the differences between WT and gene-deficient Hoxb8 neutrophils were less uniform at the different time points after infection." (PMID 33747981, 2021). "The present study using the murine HoxB8 model showed that the wild-type W83 strain upregulates TNF-α release in an MOI-dependent manner after 24 h of infection." (PMID 39936030, 2025). "Infection of gRNA targeting lncIrf8 promoter in Mx-Cas9-GFP HoxB8 MPP and induction of Cas9 by interferon generated single-cell lncIrf8 promoter KO clones." (PMID 36916882, 2023). "HoxB8 MPP were obtained from bone marrow of Mx-Cas9-GFP mice by infection with the estrogen (E2) inducible HoxB8-ER." (PMID 36916882, 2023). "**Note: HoxB8 retrovirus from one 6 cm tissue culture dish (equivalent to 10 ml HEK293T cell supernatant from two harvests) is sufficient for infection of 3×106 mouse BM cells." (PMID 36303448, 2023). "The infection of murine in vitro generated Hoxb8 neutrophils with A. phagocytophilum induced the expression of inducible or type 2 nitric oxide synthase (iNOS or NOS2) mRNA and the secretion of significant amounts of MIP-1α (CCL3), RANTES (CCL5), and TNF." (PMID 33747981, 2021). "Murine in vitro generated Hoxb8 neutrophils recognized A. phagocytophilum and secreted chemokines and cytokines upon infection." (PMID 33747981, 2021). "MVA-infection resulted in a time-dependent increase in MLKL phosphorylation in Hoxb8 and primary macrophages." (PMID 34711816, 2021). "MIP-1α production upon infection with A. phagocytophilum was unaltered in TLR7-/- Hoxb8 neutrophils compared to WT cells." (PMID 33747981, 2021). "The infection of Hoxb8 neutrophils with A. phagocytophilum has been shown previously to induce the secretion of MIP-1α, RANTES and TNF." (PMID 33747981, 2021). "The infection of Hoxb8 neutrophils with A. phagocytophilum has been shown previously to induce iNOS mRNA." (PMID 33747981, 2021). "Each TF was perturbed independently by three sgRNAs, introduced via lentiviral infection into Cas9‐expressing Hoxb8‐FL cells." (PMID 33103827, 2020). "IFN-γ R−/− Hoxb8 neutrophils showed an unimpaired chemokine and cytokine response upon infection but were unable to produce significant amounts of RANTES and TNF after IFN-γ stimulation." (PMID 28697801, 2017). "In contrast, iNOS mRNA expression was induced 1000-fold in Hoxb8 wild-type neutrophils upon infection." (PMID 28697801, 2017). "HoxB8 and HoxA9 infection induced rapid proliferation of wild type cells but only HoxB8 induced proliferation of Bcl-2−/− cells and permitted the establishment of cell lines." (PMID 24177192, 2013). "Similarly, infection with the gingipain null mutant (ΔKRAB) also prolonged HoxB8 neutrophils viability at MOI 20 and 50 for up to 48 h post-infection." (PMID 39936030, 2025). "Western blotting at 3 h post-infection revealed that both the W83 and the gingipain-null mutant (ΔKRAB) induced expression of three anti-apoptotic proteins, A1, Mcl-1, and Bcl-xL, by murine HoxB8 neutrophils." (PMID 39936030, 2025). "iNOS mRNA was hardly expressed in uninfected wild-type Hoxb8 neutrophils (μ = Ct 39.4, SD = Ct 1.7, 7 experiments), but was 100- to 1000-fold induced upon infection or LPS-stimulation at the time points 24–96 h (U = 0, n1 = n2 = 7, P = 0.0006 at 24 and 48 h p.i.)." (PMID 28697801, 2017). "As before, HoxB8 infection immortalized Bcl-2−/− progenitor cells." (PMID 24177192, 2013). "Harvest HoxB8 retrovirus from transfected HEK293T cells and concentrate retrovirus by PB/CSC precipitation for BM cell infection." (PMID 36303448, 2023). "We used Hoxb8-Cre; ROSATVA mice to induce stable expression of TVA in most dorsal horn neurons during development, enabling their infection in the adult with EnvA pseudotyped rabies viruses (SAD.RabiesΔG-GFP (EnvA))." (PMID 36752606, 2023).
infection (continued). "In essence, DAP12-/- and FcRγ-/- Hoxb8 neutrophils produced similar amounts of MIP-1α, RANTES and TNF upon infection with A. phagocytophilum." (PMID 33747981, 2021). "Upon infection with A. phagocytophilum, iNOS mRNA was expressed similarly in DAP12-/-, FcRγ-/- and WT Hoxb8 neutrophils." (PMID 33747981, 2021). "TRIF-/- Hoxb8 neutrophils secreted significantly more RANTES, TNF and IL-6 than WT cells upon infection." (PMID 33747981, 2021). "iNOS induction in WT, TLR7-/-, TLR9-/-, and TRIF-/- Hoxb8 neutrophils after infection with A. phagocytophilum was not significantly different." (PMID 33747981, 2021). "Annexin V staining of murine HoxB8 neutrophils incubated with the wild-type strain of Porphyromonas gingivalis W83 at the multiplicity of infection (MOI) of 20 and 50 revealed an increase in the viability for up to 48 h post-infection when compared to the untreated control." (PMID 39936030, 2025). "Of note, results obtained from the murine HoxB8 model did not reveal any significant difference in the NE activity at any time post-infection with the wild-type strain W83, ∆KRAB, or stimulation with Porphyromonas gingivalis-isolated LPS, or in the presence of gingipain inhibitors KYT-1 and KYT-36." (PMID 39936030, 2025). "In contrast, iNOS mRNA was not up-regulated upon infection or LPS-stimulation in TLR-5-fold-/-, MyD88-/- and MyD88-/- TRIF-/- Hoxb8 neutrophils compared to the respective uninfected or unstimulated control cells." (PMID 33747981, 2021). "Neither infection nor LPS-stimulation led to a significant induction of gp91phox mRNA in wild-type, MPO−/− or iNOS−/− Hoxb8 neutrophils." (PMID 28697801, 2017).
adenocarcinoma (1 paper, 2025). A common cancer characterized by the presence of malignant glandular cells. "Our data suggest that HOXB6 and HOXB8 regulate numerous oncogenic pathways to promote adenocarcinoma tumorigenesis." (PMID 40619489, 2025).
HOXB8 also shares sentences with these, for which no sentence is quoted: autism spectrum disorder (2 papers); glioblastoma (2); acute leukemia (1); acute myeloid leukemia (1); Aicardi-Goutières syndrome (1); amyotrophic lateral sclerosis (1); Arthritis (1); asthma (1); bladder cancer (1); brain disorder (1); cholangiocarcinoma (1); leukopenia (1); lung disease (1); non-small cell lung carcinoma (1); oesophageal adenocarcinoma (1); oral squamous cell carcinoma (1); ovarian serous carcinoma (1); pancreatic (1); pancreatic adenocarcinoma (1); pituitary adenoma (1); Rett syndrome (1); Streptococcus pneumoniae infection (1).